APP (amyloid beta precursor protein)
Diseases named in the same sentence as APP in open-access papers (continued):
Sharing a sentence is not in itself a finding about the gene and the disease.
Cognitive impairment (continued). "Since knockdown of ELK1 reduced APP amyloidogenic processing in vitro, we aimed to investigate whether knockdown of ELK1 by adeno-associated virus carrying ELK1 shRNA (AAVshELK1) could alleviate amyloid pathology and cognitive deficits in APP23/PS45 double-transgenic model mice of AD." (PMID 40307574, 2025). "Consistently, in APP/PSEN1 double‐mutant transgenic mice, an HF‐rTMS treatment (5 Hz) highlighted an improvement in learning, memory, and cognitive impairment also due to a specific modulation on the BDNF‐TrkB signaling pathway." (PMID 40530618, 2025). "Supporting this concept, studies have demonstrated that promoting M2 polarization-for instance, through TLR4 inhibition in APP/PS1 mice-exerts neuroprotective effects and ameliorates cognitive deficits." (PMID 41378217, 2025). "In APP/PS1 mice, XMU-MP-1 administration protects against cognitive deficits and reverses signs of astrocytic senescence through a mechanism requiring YAP, demonstrating that MST1 inhibition is also beneficial in non-neuronal brain cell types." (PMID 41013661, 2025). "In APP/PS1 and BV2 models, environmentally relevant doses of PS-NPs exacerbate cognitive deficits and Aβ-plaque deposition by disrupting lysosomal function and inducing microglial pyroptosis, reducing their phagocytic capacity." (PMID 41303677, 2025). "In older APP/PS1 AD model mice, cognitive impairments affect spatial learning and memory, a phenotype that is rescued by pridopidine." (PMID 41471389, 2025). "Knockout of Gal‐9 in APP/PS1 mice substantially reduced Aβ sedimentation, neuroinflammation, and cognitive impairment." (PMID 39485716, 2025). "An altered composition of indole-producing bacteria was observed in APP/PS1 mice, concomitant with compromised intestinal barrier integrity and cognitive impairment." (PMID 38360862, 2024). "In APP/PS1 double-transgenic AD mice, intravenous administration of polystyrene MPs promoted the progression of cognitive impairment by inducing neuroinflammation." (PMID 39683933, 2024). "GSK3β inhibition was observed in response to trehalose, which upregulated ERα and ERβ and protected APP/PS1 mice against dietary advanced glycation end product (dAGE)-induced neurotoxicity and cognitive impairment." (PMID 38064105, 2024). "Increasing experimental evidence indicates that hippocampal activity is altered prior to cognitive impairment and plaque detection in both animal models as well as human patients, suggesting that synaptic phenotypes may be present at early stages of overproduction of Aβ or APP-products." (PMID 39262788, 2024). "The schematic diagram showing the 9‐MF prevented long‐term cognitive impairments via cell‐specific inhibition of ROCK2 and GSK3β in APP/PS1 transgenic mice." (PMID 39563011, 2024). "APP/PS1 transgenic mice, a mouse model commonly used in AD research, harbor appearance of A‐beta plaques starting at 3 months old of age, exhibiting cognitive deficits at 7 months old of age." (PMID 38421101, 2024). "The six-months old APP/PS1 mice, which have amyloid plaques and cognitive impairment, are useful in studying neurological disorders of the brain, specifically AD." (PMID 38256233, 2024). "In an amyloid precursor protein (APP) mouse model for AD—APP23, intracerebral injection of IL-4/IL-13 increases Aβ clearance and improves cognitive deficits." (PMID 39769453, 2024). "In APP/PS1 AD mice, it was also found that TMAO is associated with and may lead to increased levels of apolipoprotein J (or clusterin, CLU), a risk factor for AD, which increases the activity of β-secretase, which is involved in amyloid accumulation, promoting cognitive impairment." (PMID 39462700, 2024). "We further investigated age‐related behavior in APP/PS1 mice using the open field, EPM (anxiety‐like behavior), and MWM (cognitive impairment) tests." (PMID 38606360, 2024).
Cognitive impairment (continued). "The 5xFAD mouse, which highly expresses mutant human APP and PSEN1, is frequently used for investigating AD pathology in vivo, including amyloid plaque formation and cognitive impairment." (PMID 38472795, 2024). "Then, we tested on APP/PS1 mice and wild-type mice with cognitive impairment phenotypes to verify the expression of hippocampal genes by qRT-PCR and to evaluate the reliability and validity of bioinformatics analysis." (PMID 37759083, 2023). "The data in the current study suggest a hitherto undisclosed link between APP processing and GM1: GM1 promotes Aβ production and plaque deposition and aggravates cognitive impairment." (PMID 37759382, 2023). "These transgenes co-segregate in the APP/PS1 mice, which develop AD-like cognitive deficits, as well as brain amyloid plaques, in a similar pattern to human AD, by around 6 months of age." (PMID 36899898, 2023). "Consistent with the progressive nature of AD, the pro-excitatory eE/I ratio in the TCx was positively correlated with higher levels of AD biomarkers (tau, Braak stage, APP, and CERAD score) and with cognitive impairment." (PMID 36538112, 2023). "In summary, 33i treatment was effective and beneficial in the APP/PS1 model, improving the cognitive impairment, reducing the amyloid pathology and neuroinflammation." (PMID 37698780, 2023). "In APP/PS1 mice, the simultaneous silencing of NLRP1 and caspase-1 reduced neuronal cell death in the cortex and hippocampus, and improved cognitive impairment." (PMID 37921870, 2023). "We found that 9-10 months old APP/PS1 mice with b-amyloid accumulation and short-term memory and cognitive deficits display a markedly reduced expression of ADAM17 in cerebral microvessels." (PMID 36937050, 2023). "In contrast, injecting Aβ-specific CD4+ TH1 and TH17 Teff cells into the brains of APP/PS1 mice has been shown to exacerbate Aβ burden, microgliosis, neuroinflammation, and cognitive impairment." (PMID 36703235, 2023). "Our data emphasize that age and sex are important variables to consider in evaluating periodontal bone tissue of APP/PS1 mice, and the cognitive impairment is more related to age." (PMID 37370108, 2023). "Studies showed that Astragalus polysaccharide alleviated cognitive impairment and β-amyloid accumulation in APP/PS1 mice and Astragaloside IV ameliorated cognitive impairment and neuroinflammation in an oligomeric Aβ induced AD mice model." (PMID 37954637, 2023). "A study using the same behavioral paradigm found a DiL impairment in 6–7-month-old APP/PS1 mice, i.e., an age at which cognitive deficits are frequently reported in this model." (PMID 37980670, 2023). "The behavioral test of APP/PS1 mice and related biological processes were extensively evaluated to demonstrate the advantageous features of the OST/BO gel in improving cognitive impairment." (PMID 37521471, 2023). "In this research study, we selected the APP/PS1 mouse as a model for AD; in this model, Aβ plaques are observed at the age of 4 months, with visible cognitive deficits with respect to spatial learning at 8 months." (PMID 36615777, 2022). "Knockout of CMKLR1 in APP/PS1 mice leads to increased Aβ deposition but also mortality and cognitive impairment." (PMID 36359817, 2022). "Six weeks of treatment with intranasal insulin rescued brain insulin signalling dysfunction, ameliorated cognitive impairments, inhibited JNK activation, increased neurogenesis and reduced Aβ accumulation and plaques in 4.5‐month‐old APP/PS1 mice." (PMID 35128745, 2022). "Dihydromyricetin (DHM) exerted neuroprotective effects in APP/PS1 mice, which significantly ameliorated memory and cognitive deficits, decreased activated microglia, reduced expression and activation of NLRP3 inflammasomes in APP/PS1 mice." (PMID 35250543, 2022).
Cognitive impairment (continued). "In APP/PS1 mouse model, TRPML1 has been reported to alleviate cognitive impairment in AD by mediating neuron autophagy and reducing autophagosome accumulation through the PPARγ/AMPK/mTOR signaling pathway." (PMID 35116093, 2022). "In this study, we found that PBMT treatment of APP/PS1 and 3xTg-AD mice lymph nodes promoted AHN to improve cognitive deficits, these effects mainly due to the upregulation of IFN-γ/IL-10 protein expression in brain tissue after PBMT treatment." (PMID 36217178, 2022). "Compared to normal wild-type mice, APP/PS1 control mice had a longer latency time (day 3 and day 5) with cognitive impairment (ADC vs. WTC, P < 0.01)." (PMID 36195875, 2022). "Following intervention with the CD38 inhibitor in APP/PS1 mice, the energy metabolism disorder was improved in the hippocampus and cortex, the level of proinflammatory cytokines was reduced, and cognitive impairment was improved." (PMID 35241173, 2022). "APN deficiency accelerates Aβ deposition and exacerbates learning and memory impairment; treatment with the APN agonist AdipoRon alleviates Aβ plaque deposition in APP/PS1 mice and cognitive impairment in 5xFAD*APN KO mice." (PMID 36077318, 2022). "The APP/PS1 mouse line represents a reliable model that exhibits Aβ deposition as early as 6 months of age and has been reported to exhibit cognitive deficits starting at 8 months of age." (PMID 36040311, 2022). "It is reported that APP/PS1 mouse shows increased Aβ plaque and cognitive deficits by the age of 4 months and 6 months, respectively." (PMID 35701825, 2022). "In male APP/PS1 mice, FA treatment ameliorated memory and cognitive impairments and suppressed Aβ deposition and p-tau levels in the brain." (PMID 35342364, 2022). "NRF2 overexpression in APP/PS1 astrocytes reduced amyloid pathology as well as glial cells reactivity (decrease in Iba1 and GFAP expression) and reversed cognitive deficits observed in APP/PS1 mice." (PMID 35892629, 2022). "Another study showed that gavage of APP/PS1 mice with geniposide at 50 mg/kg/d can effectively improve mice's exploration and memory abilities and effectively improve cognitive impairment." (PMID 34454545, 2021). "The APP/PSEN1-Tg model of AD recapitulates the early-depressive, early-anxiety and other early-cognitive impairment manifestations before developing AD, as a prodromal stage of the neurodegenerative disease." (PMID 33795014, 2021). "It was surprising to find intact cognition in 8–16 months old APP/PS1 mice using TUNL and PAL touchscreen tasks, as cognitive deficits have been reported in this model as early as 4 months of age." (PMID 34938165, 2021). "Therefore, APP cleaving enzymes such as a disintegrin and metalloprotease (ADAM) 10 and 17, may be effective targets for reducing Aβ peptide formation and function and ameliorating the cognitive deficits associated with aging." (PMID 35069206, 2021). "We found that APP/PS1 mice showed abnormalities in some aspects of cognitive function at 6 months of age, and more comprehensive cognitive impairment at 8 months of age through some simple behavioral tests." (PMID 34916926, 2021). "Upregulation of IL-4 expression in the hippocampus of APP/PS1 mice promoted β-amyloid (Aβ) clearance by microglia and ameliorated cognitive deficits." (PMID 35153675, 2021). "We also find that APP is a CMA substrate and show that Metformin reduces Aβ levels and improves cognitive impairment in the APP/PS1 mouse model of AD." (PMID 34291435, 2021). "Nicergoline has been found to enhance the cholinergic and catecholaminergic neurotransmission, improve the age-related cognitive deficits, and modulate protein kinase C (PKC)-mediated α-secretase processing of APP." (PMID 34479211, 2021). "Above data indicate that AEP activity in APP/PS1 mice brain began to increase at 5 months of age; this elevation precedes emergence of Aβ plaque and cognitive impairment." (PMID 34412639, 2021).
Cognitive impairment (continued). "APP/PS1 transgenic mice, which demonstrate age-dependent cognitive deficits, have been extensively used for AD research." (PMID 34776831, 2021). "In a study, in 5‐month‐old APP/PS1 mice, it was shown that overexpression of miR‐574 leads to cognitive impairment via neuritin regulation." (PMID 31663645, 2020). "Recent studies in APP/PS1 mice have shown that, in the early stages of AD, microRNA-34a expression increases before Aβ production and cognitive impairment." (PMID 32714136, 2020). "The repeated circling behavior in APP/PS1 mice was also reminiscent of topographical disorientation, which is common in human patients affected by mild cognitive impairment progressing to AD." (PMID 33384577, 2020). "Overall, these results suggest that monocytes are modulated in APP mice, and MDP treatments slightly improved cognitive deficits of the mice when the disease is established." (PMID 32698829, 2020). "The triple transgenic mouse model of AD (3xTg-AD) harbors presenilin 1 (PS1; M146 V), amyloid precursor protein (APP; Swe), and tau (P301 L) transgenes, and displays progressive AD-like pathology and cognitive impairments in an age-related manner." (PMID 32619874, 2020). "Ceftriaxone improves cognitive impairment of APP/PS1 mice by upregulating GLT-1-mediated uptake of glutamate and co-regulation of GLT-1 and xCT in APP/PS1 mice." (PMID 33132901, 2020). "The aim of this study was to investigate the effect of EA on cognitive impairment and the role of the JNK signaling pathway in AD model amyloid precursor protein (APP)/presenilin 1 (PS1) mice." (PMID 32116652, 2020). "Previously, the PTEN lipid phosphatase pathway has been shown to be dysregulated in APP/PSEN1 mice, leading to cognitive impairment." (PMID 32236736, 2020). "In conclusion, we discovered that GLTs relieved cognitive impairment and decreased NFT numbers in APP/PS1 transgenic AD model mice by inhibiting apoptosis and inactivating the ROCK signaling pathway." (PMID 32089787, 2020). "Four weeks of EA significantly ameliorated the cognitive impairments and inhibited JNK signaling pathway activation and APP upregulation." (PMID 32116652, 2020). "When given daily for 20 days, zerumbone significantly increased the RI of APP/PS1 mice to approximately 78%, showing that zerumbone ameliorated cognitive impairments in these mice." (PMID 32066466, 2020). "The APP/PS1 mice express a human amyloid precursor protein (APP) and human presenilin-1 (PS1), leading to the accumulation of Aβ peptides, neuroinflammation, and cognitive impairment." (PMID 33257576, 2020). "To more convincingly prove the improvement of Cef on cognitive impairment of APP/PS1 AD model mice and roles of GLT-1 in the improvement, we constructed partial GLT-1 knockout APP/PS1 mice in the present study." (PMID 33132901, 2020). "In two distinct models of Aβ precursor protein (APP) mutagenesis, the Tg2576 mouse and the APP/PS1 transgenic mouse, mTBI enhanced Aβ aggregation, and precipitated cognitive impairment of pre-symptomatic AD mice." (PMID 32848549, 2020). "In APP/PSEN1 mice, PTEN-regulated cognitive impairment presents as increased synaptic long-term depression, which is ameliorated by inhibition of PTEN with VO-OHpic, or the synthetic peptide PTEN-PDZ, which disrupts the binding of PTEN to PSD-95." (PMID 32236736, 2020). "Previous studies have reported that tolfenamic acid alleviated cognitive deficits and downregulated the expression of BACE1, APP, and phosphorylated tau in APP transgenic mice." (PMID 31049134, 2019). "Lately, novel research demonstrated that TUDCA attenuates amyloid precursor protein (APP) processing, reduces Aβ deposition and prevents cognitive impairment in APP/PS1 mice." (PMID 31757001, 2019). "In summary, we report that patients with FTLD show a global reduction of APP‐derived peptides in CSF and that this reduction correlated with FTLD‐related neurodegeneration and cognitive impairment." (PMID 31789459, 2019).
Cognitive impairment (continued). "It has been described that the APP/PS1 double transgenic mouse model develops AD pathology and cognitive impairment with increasing age." (PMID 31379578, 2019). "Efficacy of Fasudil, BMSCs, or Fasudil combined with BMSCs was determined using the MWM test in APP/PS1 Tg mice, which were screened for cognitive impairment (appreciable symptoms) at the age of 8 months and 2 weeks after the last treatment." (PMID 30061826, 2018). "In our study, the absence and structural damage of neuronal cells resulted in inhibition of BDNF-TrkB in the APP/PS1 group, appearing cognitive impairment which performance as learning and memory dysfunction." (PMID 29980225, 2018). "Ethanol exposure of mice for 4 weeks increased APP levels and BACE1 expression, promoted Aβ production, increased plaque deposition, and worsened cognitive deficits." (PMID 29759078, 2018). "In Aβ-elicited rat AD model, TSG reversed the increased amyloid precursor protein (APP) expression and the downregulation of Src and NR2B mRNA and protein levels and finally improved the cognitive impairment." (PMID 29801454, 2018). "Accordingly, we have examined both the cerebral and systemic vascular ultrastructure of young 4- to 5-month-old male APP/PS1 mice at the age when cerebral amyloid plaques begin to accumulate, prior to development of both CAA and cognitive deficits." (PMID 28741167, 2017). "Perhaps as a result of elevated neuropathology, cognitive impairments are also generally greater in female mice, including Tg2576, APP/PS1, CRND8, APP/TTA, 3xTg-AD, and rTg4510 models." (PMID 29273078, 2017). "These structures suggest a breakdown of the BBB in 4- to 5-month-old APP/PS1 mice, which is prior to the onset of cognitive impairment in this murine AD model." (PMID 28741167, 2017). "Our water maze test, Y maze, and fear condition results showed that 5-HT6 antagonist SB271046 recovered cognitive impairment in APP/PS1 mice, indicating that 5-HT6 has a close relationship with the cognition of APP/PS1 mice." (PMID 28931427, 2017). "Moreover, mutations in the APP, PS1 and PS2 genes cause an altered protein folding process with malfunctions in the endoplasmic reticulum (ER), altered mitochondrial function and a decrease in myelin formation associated with cognitive impairments during the aging process." (PMID 28072821, 2017). "Besides, SB271046, 5-HT6 antagonist, could recover the cognitive impairment of APP/PS1 mice." (PMID 28931427, 2017). "We firstly detected the changes of HPA axis and HPG axis of APP/PS1 mice, and the correlations between cognitive impairment and them." (PMID 27049828, 2016). "For endocrine hormone contributing to cognitive impairment, CORT, LH and FSH were important in SAMP8, while ATCH and GnRH in APP/PS1 mice." (PMID 27049828, 2016). "The imbalance between Th1 and Th2 cell contributed to cognitive impairment in SAMP8 mice and APP/PS1 mice." (PMID 27049828, 2016). "Therefore, the disrupted CFC in APP-KO mice observed here may constitute a network correlate of dysfunctional signaling and cognitive deficits that have been previously associated to the lack of APP9." (PMID 26905287, 2016). "In order to obtain the NIM molecular network correlated with cognitive impairment, we submitted the factors significantly correlated with cognition of SAMP8 mice and APP/PS1 mice, obtained by Pearson correlation analysis, to MetaCore database, respectively." (PMID 27049828, 2016). "Pro-inflammatory factor IL-23 contributed to cognitive impairment in SAMP8, while colony stimulating factor G-CSF in APP/PS1 mice." (PMID 27049828, 2016). "However, even if the strength of the GRK5 deficiency is not sufficient to cause cognitive impairment, it is sufficient to make the animals more vulnerable to cognitive impairment from additional insults, such as the over-expression of Swedish APP in the GAP mice." (PMID 27193825, 2016).